PLIN2 (perilipin 2)
Diseases named in the same sentence as PLIN2 in open-access papers (continued):
Sharing a sentence is not in itself a finding about the gene and the disease.
ischemic stroke (1 paper, 2025). A stroke disorder caused by obstruction of blood flow to the brain, due to thrombotic (local blood clot formation) or embolic (due to a blood clot or other material traveling from another site) event. "Furthermore, in the context of ischemic stroke, the expression of perilipin-2 (Plin2) is upregulated, and the expression of ATP-binding cassette transporter A1 (ABCA1) is downregulated, leading to increased lipid droplet formation and impaired cholesterol clearance in TREM2-deficient microglia." (PMID 40242752, 2025).
keloid (1 paper, 2024). An irregularly shaped, elevated mark on the skin caused by deposits of excessive amounts of collagen during wound healing. "In summary, we identified AKR1C3, PLIN2, SOCS2, SLC38A1, and SNCA as characteristic genes associated with ferroptosis in keloids through comprehensive transcriptomic data analysis." (PMID 39834787, 2024). "In summary, the upregulation of AKR1C3 and PLIN2 in keloids may inhibit ferroptosis by affecting oxidative stress, as well as lipid metabolism and storage, thereby promoting cell proliferation and fibrosis, which further contributes to scar tissue formation." (PMID 39834787, 2024). "The upregulation of PLIN2 in keloids may influence the scar healing process by promoting cell proliferation and reducing autophagy." (PMID 39834787, 2024). "As shown in, at the protein level, the expression of PLIN2 and AKR1C3 was significantly increased in keloid samples compared to normal samples, whereas the expression of SOCS2, SLC38A1, and SNCA was significantly decreased." (PMID 39834787, 2024). "Additionally, as depicted in, at the mRNA level, there was also a significant increase in the expression of PLIN2 and AKR1C3 in keloid samples, and a significant decrease in the expression of SOCS2, SLC38A1, and SNCA." (PMID 39834787, 2024).
Lipid storage disease (1 paper, 2013). "In this study, we showed that PLIN2 was over-expressed in TGCV patient cells at the protein level, which was in good agreement with previous studies in the context of lipid storage diseases." (PMID 24360150, 2013).
liver failure (1 paper, 2022). A liver disease characterized by the liver losing or has lost all of its function. "Seven differentially expressed ferroptosis-related genes (Hmox1, Epas1, Sirt1, Slc3a2, Jun, Plin2 and Zfp36) were obtained through the intersection of ferroptosis-related genes in the FerrDb database with DEGs in the GSE60088 dataset, and all of these genes were up-regulated in liver failure." (PMID 35923893, 2022).
minimal change disease (1 paper, 2022). "Perilipin-2 has been implicated in several metabolic, cardiovascular, and kidney diseases, including the demonstration of glomerular and tubular perilipin-2 in minimal change disease and diabetic glomerulosclerosis." (PMID 36613637, 2022).
Niemann-Pick disease (1 paper, 2023). A group of inherited, severe metabolic disorders in which sphingomyelin accumulates in lysosomes in cells. "MARCH6 targets several other lipid-related substrates, including perilipin-2 (PLIN2), Niemann-Pick disease (NPC) intracellular cholesterol transporter 1 (NPC1), and the bile salt export pump (BSEP)." (PMID 37779139, 2023).
non-alcoholic fatty liver (1 paper, 2026). A benign form of fatty non-alcoholic fatty liver disease where the disease has not yet progressed to the inflammation of liver. "Two genes, ACAA2 and PLIN2, were significantly altered at both the transcript and protein levels and may be crucial for maintaining mitochondrial function in early non-alcoholic fatty liver (NAFL)." (PMID 41654732, 2026).
Norrie disease (1 paper, 2021). A rare X-linked genetic vitreoretinal condition characterized by abnormal retinal development with congenital blindness. "PPI analysis has indicated that FZD4 protein interactome via PLIN2 as well as the MAP kinase signaling pathway to be a likely link bridging the functional relationship between retinoschisis and Norrie disease." (PMID 34039417, 2021).
odontogenic tumor (1 paper, 2025). "Increased perilipin-1 and perilipin-2 (also known as adipophilin) expression has been linked to EMT, a key process in odontogenic tumor invasion." (PMID 40699660, 2025).
osteoarthritis (1 paper, 2024). A noninflammatory degenerative joint disease occurring chiefly in older persons, characterized by degeneration of the articular cartilage, hypertrophy of bone at the margins and changes in the synovial membrane. "Puerarin, ferroptosis, and osteoarthritis share four targets: PLIN2, PTGS2, VEGFA, and IL6." (PMID 37548663, 2024). "Common targets of puerarin, ferroptosis, and osteoarthritis include PLIN2, PTGS2, VEGF, and IL6." (PMID 37548663, 2024).
osteosarcoma (1 paper, 2022). A usually aggressive malignant bone-forming mesenchymal neoplasm, predominantly affecting adolescents and young adults. "This was true for both, LDs and PLIN2 expression in both osteosarcoma cell lines." (PMID 35834072, 2022). "Lipid droplet coating proteins of the perilipin family (PLIN2, PLIN3) were detected in both, tumor samples and canine osteosarcoma cell lines D-17 and COS4288 as well." (PMID 35834072, 2022). "Lipid droplets, PLIN2, and PLIN3 were detected in osteosarcoma tissue samples as well as in 2D and 3D cultivated D-17 and COS4288 cells." (PMID 35834072, 2022).
Pick disease (1 paper, 2025). A rare neurodegenerative disorder leading to dementia. "Lastly, we examined whether PLIN2 immunoreactivity was also present in non-TDP-43-related FTLD cases, such as the frontal cortex of Pick’s disease (FTLD-tau)." (PMID 40906043, 2025).
Renal neoplasm (1 paper, 2021). The presence of a neoplasm of the kidney. "When PLIN2 stained more than 10% of cells in a sample (scored as 2 or 3), 90% of ccRCC cases were detected with a 100% specificity distinguishing ccRCC from other renal neoplasms." (PMID 34482820, 2021).
respiratory failure (1 paper, 2021). The significant impairment of gas exchange within the lungs resulting in hypoxia, hypercarbia, or both, to the extent that organ tissue perfusion is severely compromised. "Moreover, serum PLIN2 levels were associated with severe respiratory failure potentially reflecting a moribund state." (PMID 34572396, 2021). "Moreover, those patients with serum PLIN2 levels above the median had a better survival, again, reflecting the role of severe respiratory failure that was associated with reduced serum PLIN2." (PMID 34572396, 2021). "This contradiction is partly explained by the marked decrease of PLIN2 concentrations in severe respiratory failure, which in turn results in increased mortality." (PMID 34572396, 2021). "Because serum PLIN2 was diminished in patients with severe respiratory failure, defined as PaO2/FiO2 < 100, we analyzed if among this subgroup serum PLIN2 concentrations below or above the median were associated with ICU mortality." (PMID 34572396, 2021). "Future studies are warranted to assess whether PLIN2 measurements can enhance the diagnostic and prognostic value of ADMA, especially in the context of the observed changes in PLIN2 levels in severe respiratory failure." (PMID 34572396, 2021). "Although this is consistent with studies previously reporting about the relevance of PLIN2 in age-related diseases, those patients with serum PLIN2 levels above the median had worse outcomes, which may reflect the detrimental outcome of patients with severe respiratory failure." (PMID 34572396, 2021).
ST Elevation Myocardial Infarction (1 paper, 2021). A myocardial infarction that produces elevation in the ST segments of the ECG. "Recent studies highlighted the importance of PLIN2 in cardiomyocyte lipid accumulation and were able to connect PLIN2 to coronary microvascular obstruction and infarct size in patients with ST-elevation myocardial infarction and major adverse cardiovascular events during follow-up." (PMID 34572396, 2021).
tuberculosis (1 paper, 2025). A chronic, recurrent infection caused by the bacterium Mycobacterium tuberculosis. "Because Plin2 is the marker of foamy macrophages in the lungs of TB patients and M. tuberculosis-infected C3HeB/FeJ mice, we referred to the Plin2+ cluster as the foamy macrophage population." (PMID 40843005, 2025).
uremia (1 paper, 2021). A clinical syndrome associated with the retention of renal waste products or uremic toxins in the blood. "THP-1 cells treated with PMA and then exposed to uremia, showed increased ABCA1, CD36, and PLIN2 expression compared to macrophages exposed to normal serum." (PMID 33536542, 2021).
Uterine leiomyoma (1 paper, 2022). The presence of a leiomyoma of the uterus. "However, in uterine leiomyoma, PLIN2 deficiency reprogrammed cells to a hyperproliferation phenotype." (PMID 35372038, 2022).
ZIKV infection (1 paper, 2023). "Corroborating these data, treatment with iDGAT-1 decreased the mRNA expression of PLIN-2, a structural LD protein induced by ZIKV infection." (PMID 36882750, 2023).
tumor (89 papers, 2007 to 2026). "The results demonstrated that PLIN2 suppression caused decreased permeability in mouse models, leading to less ascites and tumor weight." (PMID 39921309, 2025). "PLIN2, a lipid droplet-associated protein, has been implicated in tumor progression via lipid metabolic pathways." (PMID 40640171, 2025). "Here, our results proposed abnormal LDs accumulation as a tumor promoting effector and overexpression of LDs coat protein PLIN2 as a risk factor for OSCC prognosis." (PMID 39875372, 2025). "Similar correlations between PLIN2 and inflammatory cytokines have been observed in tumor-associated macrophages as well as in THP-1 cells." (PMID 37781924, 2023). "Plin2 expression in different tumor cells confers susceptibility to cell death induced by Trip13 depletion as well as treatment with paclitaxel, a spindle‐interfering drug commonly used against different cancers." (PMID 36031387, 2022). "Specifically, perilipin 2 confers susceptibility to Trip13‐knockdown‐ and antimitotic‐drug‐induced cell death, allowing for stratification for paclitaxel‐treatment‐responsive tumor cells." (PMID 36031387, 2022). "The results showed that in the tumor center and invasive tumor front, the high expression of PLIN2 was associated with a higher postoperative metastasis rate." (PMID 35372038, 2022). "UMAP PLOT visualized the cells in each cluster, and the data showed that PLIN2 was mainly expressed in NK cells, followed by tumor-associated macrophages (TAMs) in HNSCC." (PMID 35372038, 2022). "CD68+ tumor-associated macrophages (TAMs), instead of T cells and B cells, were found to be the main resource of PLIN2 in OSCC stroma and lung, pancreas, prostate, and testis." (PMID 35372038, 2022). "These consistent associations of serum PLIN2 with malignancy even during critical illness underline its potential capacity as a tumor marker for routine diagnostics." (PMID 34572396, 2021). "We utilized TIMER to explore potential associations between the expression of PLIN2 and both tumor purity and infiltration of immune cells in various cancers." (PMID 33203856, 2020). "PLIN2 was significantly associated with tumor purity and infiltration of B cells, CD4+ T cells, CD8+ T cells, neutrophils, macrophages, and DCs." (PMID 33203856, 2020). "Similarly, we discovered that CD68+ PLIN2+ tumor-associated macrophages induced immune suppression, accompanied by high levels of immune checkpoint molecules." (PMID 38554152, 2024). "Therefore, in our study, we examined the expression pattern and clinical diagnostic and prognostic value of PLIN2 protein in the tumor microenvironment (TME) including tumor cells (TCs), fibroblast-like cells (FLCs), and tumor-infiltrating immunocytes (TIIs)." (PMID 35372038, 2022). "In addition, NAC1 mRNA (which is encoded by NACC1), a transcriptional regulator of FASN in tumor cells, was also increased, as well as PLIN2 (perilipin 2) mRNA, which is involved in lipid droplet formation." (PMID 34206240, 2021). "In addition to metabolic and cardiovascular associations, PLIN2 has been described as a potential tumor marker in prevalent malignancies such as colorectal or lung carcinoma." (PMID 34572396, 2021). "We demonstrate that hypoxia upregulates the key desaturase, stearoyl-CoA desaturase-1 (SCD1), and the lipid droplet (LD) protein PLIN2, thus promoting lipid metabolic adaptation, cell proliferation, migration, and tumor growth." (PMID 42292857, 2026). "Given our finding of high PLIN2 expression in CRC clinical samples, we subsequently focused our study on elucidating the role of PLIN2 on CRC tumor cells and related mechanisms." (PMID 40640171, 2025). "In subcutaneous xenograft model and CRC orthotopic model, we found that overexpression of PLIN2 promoted tumor growth." (PMID 40640171, 2025). "Previous studies indicate that HIF-2α transcriptionally regulates Perilipin 2 (PLIN2), thereby stabilizing endoplasmic reticulum homeostasis and promoting tumor growth." (PMID 39781455, 2025).
tumor (continued). "We observed that the tumor weight in the PLIN2 overexpression group was greater than that in the control group, which was reversed by the CD36 inhibitor." (PMID 40640171, 2025). "We presently found that PLIN2 is highly expressed in both macrophages and tumor cells by spatial transcriptome, and found that PLIN2 promotes macrophage M2 polarization." (PMID 40640171, 2025). "This modification allows the molecular chaperone HSC70 to recognize PLIN2/3, promoting the degradation of lipid droplets (LDs) and PLIN2/3 via the lipophagy pathway, thereby facilitating tumor initiation and progression." (PMID 41408408, 2025). "Overexpression or suppression of PLIN2 can enhance or inhibit tumor cell migration, invasion, and vascular permeability in vitro, which is also confirmed in vivo." (PMID 39921309, 2025). "Mechanistically, PLIN2 accelerates CRC progression via a dual mechanism: it induces macrophage reprogramming towards the tumor-promoting M2 phenotype, while simultaneously triggering the CD36-dependent EMT cascade in CRC cells." (PMID 40640171, 2025). "Results showed that Perilipin 2 staining was significantly increased in TA muscle of KPC tumor-bearing mice compared to controls." (PMID 40655023, 2025). "In accordance with the in vitro results, both ascites formation and tumor metastasis were harnessed by PLIN2‐targeting liposomes." (PMID 39921309, 2025). "Coating proteins such as PLIN2 is ubiquitinated by the Itch E3 ligase, facilitating lipid droplet (LD) degradation and releasing free fatty acids (FFAs) to support tumor metabolism." (PMID 40370434, 2025). "Meanwhile, PLIN2 significantly affects the generation and breakdown of lipid droplets, which provide energy for tumor cells through ketone metabolism." (PMID 41223031, 2025). "A previous study found that, when energy and nutrients are scarce in the TME, CHKα2 in tumor cells can activate its protein kinase function and phosphorylate PLIN2/3." (PMID 41408408, 2025). "Abnormal lipid metabolism can enable tumor cells to establish an immunosuppressive network and multiple immune proteins nucleated around PLIN2 in response to lipopolysaccharide." (PMID 38554152, 2024). "In subsequent mechanistic analyses, TRIB3 was found to promote the accumulation of LDs in tumor cells through its ability to stabilize PLIN2, thereby alleviating ER stress and facilitating more rapid progression of ccRCC." (PMID 38561354, 2024). "PLIN2 depletion decreased lipid droplets, enhanced tumor cell cytotoxic endoplasmic reticulum stress, and inhibited the tumorigenic capacity of xenografts." (PMID 38649345, 2024). "Recent studies have shown that HIF2α/PLIN2 promotes lipid storage and tumor growth in ccRCC in vivo and in vitro." (PMID 38263248, 2024). "The HIF-2α/PLIN2 lipid storage axis suppresses cytotoxic endoplasmic reticulum stress to promote lipid storage and tumor cell proliferation." (PMID 38649345, 2024). "The overexpression of PLIN2 protected LD against autophagy and macrophages were the main source of PLIN2 in tumor microenvironment, researches also reported that high expression of PLIN2 induced immune suppression." (PMID 38035339, 2023). "A previous study reported increased PLIN2 expression under hypoxic conditions, which in turn promoted increased lipid storage and utilization in tumor cells, which provided favorable conditions for invasive infiltration of cancer cells." (PMID 37189627, 2023). "shRNA mediated knockdown of PLIN2 in 786-O and A498 cell lines renders the tumor cells vulnerable to oleic acid–induced cell death which is consistent with decreased ability to store lipids within LDs." (PMID 36831657, 2023). "Among them, the mRNA expression level of PLIN1 gradually decreased with the increase in tumor grade, while PLIN2 showcased an increasing trend." (PMID 37189627, 2023). "We here aimed to investigate the heterogeneous functions of PLIN2 in the tumor microenvironment and immune regulation." (PMID 35372038, 2022).